SFTPC (surfactant protein C)
Diseases named in the same sentence as SFTPC in open-access papers (continued):
Sharing a sentence is not in itself a finding about the gene and the disease.
cancer (22 papers, 2001 to 2026). A tumor composed of atypical neoplastic, often pleomorphic cells that invade other tissues. "Medical literature supports SFTPC’s role in enhancing the anti-cancer immune environment, with low expression linked to poor LUAD prognosis." (PMID 40501071, 2025). "Using immunohistochemistry, we then determined the protein level of SFTPC in the carcinoma and para-carcinoma tissues of 52 patients from the Tangdu Hospital." (PMID 37955668, 2023). "Consistent with the mRNA level, the protein level of SFTPC was significantly decreased in carcinoma tissues." (PMID 37955668, 2023). "Cancer cells in the S components upregulated SOX4 and CEACAM5 and downregulated pro-inflammatory factors such as SCGB1A1 and SFTPC in comparison with cancer cells in the GG components." (PMID 35874770, 2022). "Integrin β4 overexpressed on 231‐exo interacts with surfactant protein C (SPC) on cancer cells and is specifically internalized by non–small cell lung cancer cells." (PMID 36054073, 2022). "Differential gene expression analysis showed overexpression of classic epithelial genes (for example, SFTPC and STEAP1), genes associated with cancer (for example, CLDN6) and regulators of EMT (for example, VIM, FN 1 and CDH2) in Oncopig LC versus normal pig lung tissues." (PMID 41407936, 2026). "Differential gene expression analysis showed overexpression of classic epithelial genes (e.g., SFTPC and STEAP1), genes associated with cancer (e.g., CLDN6), and regulators of EMT (e.g., vimentin, fibronectin 1, and N-cadherin) in Oncopig LC versus normal pig lung tissues." (PMID 39975891, 2025). "SFTPC was significantly downregulated in carcinoma tissues relative to normal tissues." (PMID 37955668, 2023). "Similar to the overall transcriptional profile of cancer cells in the GG component samples, surfactant-associated proteins (SFTPA1, SFTPA2, SFTPB, SFTPC, and SFTPD) were highly expressed, and the expression level was higher than that of other cancer cell subclusters of the GG component samples." (PMID 35874770, 2022). "Several factors, including EZH2, SFTPC, IGFBP5, ELN and EDN2, are regulated by NFIB, which have considerate values in the tumour microenvironment, advancing cancer impulsiveness, angiogenesis, migration and spread." (PMID 37845675, 2023). "Cancer cells were identified with canonical markers of LUAD and alveolar epithelial cells (e.g., SFTPB, SFTPC, EPCAM, NAPSA, and NKX2-1)." (PMID 35874770, 2022). "In comparison to ciliated, Club/Clara cells, pulmonary alveolar type 1 (AT1) and pulmonary alveolar type 2 (AT2), the EGFRex19 cancer cell cluster was characterized by high expression of NPC2 and surfactant genes SFTPB, SFTPC, and SFTPD." (PMID 33712615, 2021). "Further investigations of the remaining genes such as FN1, EEF1A1, COL1A1, SFTPB, SFTPC, and ATP1A1 will shed light on the identification of novel biomarker genes for a pan-cancer cohort." (PMID 31324856, 2019). "First, we used the SingleR package and the known markers of cancer and alveolar cells to identify a cancer cluster and alveolar cluster; EPCAM and SOX4 were used to mark the cancer cluster; SFTPC and SFTPA1 to mark the alveolar cluster; CAPS and TPPP3 to mark epithelial cells." (PMID 33783985, 2021). "KRT19, CEACAM5, EPCAM, DSG3, SFTPA, SFTPC and SFTPB mRNA levels were initially validated by real-time reverse transcription PCR-based quantification in 16 NSCLC tumors and 22 LNs and 12 PB samples from individuals without known cancer." (PMID 23671585, 2013). "Most slides from cancer-free tissue lacked expression of CCND1, CD44, CDH1, EGFR, ERBB2, KIT, keratins, NOTCH1, PAK1, PTGS2, SNAI1, and VIM but showed staining of MUC1, HIF1A, NKX2-1, SFTPC, and STAT3, which were also found in AdCa." (PMID 23028920, 2012).
tumor (22 papers, 2007 to 2025). "The loss of SHROOM4 further promotes tumor progression and metastasis by upregulating the expression of SFTPC, thereby enhancing the Wnt/β-catenin signaling pathway." (PMID 41573567, 2025). "The gene encoding surfactant protein C (SFTPC) is deleted in 71% of the NSCLC tumor tissues." (PMID 33170151, 2020). "In situ hybridization not only corroborated the increased expression of Cxcl1 in Stat3-deficient tumours but also identified the tumour cells as the main cellular origin of Cxcl1 as confirmed by staining for the alveolar type 2 cell-specific marker SP-C (surfactant protein C) in serial sections." (PMID 25734337, 2015). "SHROOM4 likely controls tumor progression and metastasis via the Wnt/β-catenin signaling pathway through the modulation of SFTPC." (PMID 41573567, 2025). "SFTPC protein levels were downregulated in tumor tissues, whereas PI3K, p-PI3K, AKT, p-AKT, mTOR, p-mTOR, RPS6KB1, and p-RPS6KB1 protein levels were upregulated." (PMID 37955668, 2023). "SFTPC expression was significantly reduced in both subgroups of cells from the stage IV primary tumor sample, GSM3516665." (PMID 33170151, 2020). "Immunohistochemical analyses revealed that tumors were negative for CC26, a Clara cell protein and positive for surfactant protein-C, a type II pneumocyte marker, indicating that the tumor cells had a type II cell-like phenotype." (PMID 17726540, 2007). "Assessment of epithelial marker genes showed similar expression scores across fresh and FFPE tissue samples, as EPCAM, KRT5, SCGB3A2, FOXJ1, AGER and SFTPC marked tumor epithelial, Basal, Transitional, Ciliated, AT1, and AT2 cells, respectively, across the datasets." (PMID 38300468, 2024). "Tumor samples and corresponding organoids also displayed a concordant expression pattern of Surfactant protein C (SFTPC), suggesting that alveolar type 2 (AT2) cells could be the cells of origin of these SFTPC+ samples." (PMID 32771979, 2020). "Second, to test whether CCA/SFTPC double positive cells might be the source of emergence of a separate tumor type, we co-stained our AT2 marker panel with antisera to detect expression of club cell antigen (CCA)." (PMID 31452510, 2019). "It illustrated that overexpression of SFTPC inhibiting EMT process of NSCLC cells was relevant to upregulating SOX7 and repressing WNT/β-catenin pathway in tumor xenograft models." (PMID 39346732, 2024). "SFTPC was dramatically downregulated in NSCLC tissues from TCGA database and 40 out of 46 collected clinical LUAD tissues compared with adjacent non-tumor tissues." (PMID 39346732, 2024). "While tumours mainly arose in the bronchi and bronchioles after targeting KRT14+ cells, they were restricted to peripheral locations when SCGB1A1+ or SFTPC+ cells were targeted." (PMID 34354223, 2021). "Therefore, in our present study, the function and molecular mechanism of the AT2 cells marker gene SFTPC in EMT process of NSCLC cells were investigated in human NSCLC cell lines, tumor xenograft models and clinical NSCLC tissues." (PMID 39346732, 2024). "Our qRT‐PCR results revealed that the expression levels of TNFSF10 (p < 0.01), ECM1 (p < 0.01), and RNF213 (p < 0.01) were significantly increased in advanced LUAD tumor cells, whereas the expression of SCGB3A2 (p < 0.01), SCGB3A1 (p < 0.01), and SFTPC (p < 0.01) was increased in early LUAD." (PMID 33783985, 2021). "KRT5+ basal cells did not produce any tumours, whereas ciliated (Forkhead box J1, FOXJ1+) and alveolar Type II (Surfactant protein C, SFTPC+) gave rise to LUAD." (PMID 34354223, 2021).
infection (17 papers, 2009 to 2025). The state of being infected such as from the introduction of a foreign agent such as serum, vaccine, antigenic substance or organism. "Through the infection of type II alveolar cells, SARS-CoV-2 interferes with the production of pulmonary surfactant, of which surfactant protein C is a key component, thus causing an increase in surface tension, lastly driving to alveolar collapse." (PMID 35326463, 2022). "Therefore, the stable SFTPC-overexpressing A549 and H1299 cell lines (termed A549-SFTPC and H1299-SFTPC) and control cell lines (termed A549-Control and H1299-Control) were established successfully by lentivirus infection for exploring the functions of SFTPC in NSCLC." (PMID 39346732, 2024). "Infection led to downregulation of surfactant genes (SFTPA1, SFTPC, SFTPD), cellular transition from functional ATIIs to proliferative ATIIs (mitotic), and PATS-like states, mimicking injury-induced alveolar regeneration pathways overserved in vivo." (PMID 41502560, 2025).
adenocarcinoma (5 papers, 2020 to 2025). A common cancer characterized by the presence of malignant glandular cells. "While alterations in the Cdkn2a gene are associated with NSCLC, surfactant protein C is a marker of alveolar type II cells, which have been believed to be the original cell source of adenocarcinomas and NSCLC." (PMID 34912233, 2021). "Similar expression patterns were observed in both groups when analyzing lung-specific markers, such as the tracheal club cell marker Scgb1a1 (CC10), the alveolar type II marker surfactant protein C (SftpC), and the adenocarcinoma marker thyroid transcription factor-1 (TTF1)." (PMID 40896696, 2025). "The expression of a second adenocarcinoma differentiation marker, SFTPC, was significantly reduced by AdSLFN12 treatment in only one LUAD cell (HCC827), while AdSLFN12 significantly reduced HOPX mRNA levels in two LUAD cells (HCC827 and H23) with no significant changes in LUSC cells." (PMID 32987632, 2020).
autosomal dominant disease (1 paper, 2023). Autosomal dominant form of disease. "Surfactant protein C (SP-C) dysfunction is a rare autosomal dominant disease due to a mutation in the SFTPC gene." (PMID 36670712, 2023).
respiratory disease (1 paper, 2023). "Initial testing for genetic causes of respiratory disease and PAH (including sequencing for FOXF1, SFTPB, SFTPC, ABCA3) was negative." (PMID 36878902, 2023).
SFTPC also shares sentences with these, for which no sentence is quoted: meningitis (5 papers); pneumococcal infection (5); pneumonia (3); acute respiratory distress syndrome (2); bacteremia (2); childhood interstitial lung disease (2); influenza (2); pulmonary alveolar microlithiasis (2); Sepsis (2); Autoimmunity (1); bacterial meningitis (1); bronchiectasis (1); bronchopulmonary dysplasia (1); CHILD syndrome (1); COPA syndrome (1); dementia (1); genetic disorders (1); Hernia (1); Klebsiella pneumonia (1); Lung Injury (1); lung squamous cell carcinoma (1); meningococcal diseases (1); middle ear infections (1); Obesity (1); otitis media (1); ovarian carcinoma (1); pneumococcal meningitis (1); pneumonic plague (1); radiation pneumonitis (1); Respiratory distress (1).
A further 4 diseases each share a sentence with SFTPC in 1 paper.